INS (insulin)
Diseases named in the same sentence as INS in open-access papers (continued):
Sharing a sentence is not in itself a finding about the gene and the disease.
diabetes (continued). "However, exercise-induced improvement in insulin signaling is not exclusively restricted to increased GLUT4 protein expression, as its concentration is similar in sedentary diabetics and insulin-sensitive control subjects." (PMID 23691290, 2013). "The United Kingdom Prospective Diabetes Study (UKPDS 49), demonstrated that long-term monotherapy with either insulin, sulfonylureas, or metformin could not sustain the glycemic control initially achieved (HbA1c <7%)." (PMID 23958390, 2013). "We tested whether UCPCR could be a surrogate measure of IR by examining the correlation of UCPCR with serum insulin, C-peptide and HOMA2 (Homeostasis Model Assessment 2)-IR in participants without diabetes and with chronic kidney disease (CKD)." (PMID 24353253, 2013). "As PGC-1α is believed to signal via insulin, whether PGC-1α might be involved in cardiac benefits independent of changes in blood glucose or insulin in diabetes is currently unknown." (PMID 23936397, 2013). "Therefore, it is an interesting observation that although a direct activation of insulin-producing beta cells via TLR4 impairs their function, the absence of TLR4 results in an acceleration of diabetes development." (PMID 24086519, 2013). "Among subjects with diabetes detected by OGTT (regardless of HbA1c), those with raised FPG differed from those with isolated raised 2hPG by being younger, predominantly men and more insulin resistant." (PMID 23365572, 2013). "Other clinical trials demonstrated that insulin infusions alone, without glucose substrate, could improve perioperative outcomes in CABG patients with and without diabetes mellitus in the presence of hyperglycemia." (PMID 23209941, 2012). "Although ODN1612 did not further reduce obesity or improve diabetes compared to those treated with PBS, ODNR01 further improved type-2 diabetes significantly, including glucose tolerance, insulin sensitivity and serum insulin levels." (PMID 23027613, 2012). "Taken together, these data indicate that metabolic pathways, cell cycle, apoptosis, and insulin and VEGF signalling are unique targets of stress-induced ATF3, whereas diabetes mellitus and calcium signalling, but not cell cycle and apoptosis, are unique targets of ATF3 expressed in cancer cells." (PMID 22046379, 2011). "In this study, 6 g/d of reduced viscosity BBG consumption over 12 weeks improved insulin sensitivity (i.e. reduced fasting insulin and HOMA-IR) in generally healthy study subjects with baseline hyperglycemia, but without a prior diagnosis of diabetes mellitus." (PMID 21846371, 2011). "In comparison with subjects without diabetes by HbA1c criterion, those with newly diagnosed diabetes by HbA1c criterion had higher serum FPG, 2hPG, HDL, TC, and fasting insulin levels in men and higher WC, serum FPG, 2hPG, CRP, and fasting insulin levels in women." (PMID 21076541, 2010). "Two autoimmune diabetes models were studied, the non-obese diabetic (NOD) mouse and the rat insulin promoter (Rip) CD80×lymphocytic choriomeningitis virus glycoprotein (GP) bi-transgenic mouse, an inducible, experimental autoantigen-specific diabetes (EAD) model." (PMID 19287497, 2009). "Unfortunately we did not measure insulin increment in non-GDM women at follow-up; hence we do not know whether deteriorating β-cell function was a predictor of diabetes in them." (PMID 17640759, 2007). "Insulin-dependent diabetes mellitus (IDDM) is a chronic diseasecharacterized by T-cell-dependent autoimmune destruction of theinsulin-producing β cells in the pancreatic islets ofLangerhans, resulting in an absolute lack of insulin." (PMID 16864906, 2006). "Modulation of these receptors by lack of insulin and IGF-I may contribute to CNS disturbances, cardiovascular, respiratory and urinary complications resulting from diabetes." (PMID 15857517, 2005).
diabetes (continued). "However, other well-designed clinical trials found negligible or no significant impact on critical diabetes parameters such as fasting blood glucose (FBG), hemoglobin A1c (HbA1c), or insulin resistance markers following dietary or supplemental intake of lycopene-rich tomato products." (PMID 40563946, 2025). "Together, these studies suggest that insulin and glucose have opposed effects on FGF23 levels, but these effects may also be context-dependent, as insulin clamping did not lead to increased FGF23 levels in individuals without diabetes." (PMID 40237064, 2025). "Furthermore, the third strength is that this work focused exclusively on CGM initiation in people with T2D who do not use insulin, as people with T2D who do not use insulin and who use CGM is a segment of the diabetes population that has been evaluated less frequently than others." (PMID 39793006, 2025). "The glucose decrease rate on IV insulin was faster in the Late group (median, 0.24 mg/dL [interquartile range {IQR}, 0.10–0.46] per minute vs. 0.14 mg/dL [0.06–0.31] per minute; p = 0.001) but was nonsignificant in the newly diagnosed and established diabetes subanalyses." (PMID 39136541, 2024). "In humans, compared to the NOND group, the diabetes (obese or nonobese) groups exhibited negative correlations between adiponectin and IL-2 and IL-23, while showing positive correlations with ENA78, eotaxin, and IP-10, along with positive correlations between leptin and insulin and IL-23." (PMID 39474247, 2024). "However, since 150 mg/kg of alloxan showed comparable induction rates, lower insulin requirements, and no adverse effects like DKA when compared to 200 mg/kg of alloxan, it is considered a more stable concentration for inducing diabetes and managing hyperglycemia with insulin." (PMID 39070316, 2024). "In yet another study, patients without diabetes with IBD were treated with anti-tumor necrosis factor alfa to examine insulin resistance with regards to insulin concentrations and HOMA-IR, showing a significantly improved insulin sensitivity compared with controls treated with aminosalicylates." (PMID 39605944, 2024). "They seem to be drugs of choice in metabolic control of diabetes and possibly nephroprotection in patients with T2D and advanced CKD who still do not need insulin (only a handful of antihyperglycemic agents may be used in CKD stages 4 and 5, including insulin)." (PMID 39684653, 2024). "Other than directly increasing complications related to diabetes in patients with COVID-19, challenges in managing DKA have been reported, particularly in resource-limited settings where protocols are not in place and where there is no or limited access to computerized insulin infusions." (PMID 39060948, 2024). "The person with diabetes previously lacked confidence with counting carbohydrates, and based on feedback from the case presentation, the PCP also learned to empower her to bolus with a set insulin dose based on the size of the meal (eg, small meal and large meal)." (PMID 37535407, 2023). "More than 90% of all instances of diabetes mellitus are type 2 diabetes mellitus (T2DM), which is characterized by a combination of two different factors: inability of the pancreatic β-cells in producing sufficient amounts of insulin and lack of insulin adsorption by its targeted cells." (PMID 37441501, 2023). "As the high predictive value of stress hyperglycemia for the prognosis of AMI may be related to its effects on myocardial metabolism and insulin treatment for DM, we also evaluated the predictive potential of the SHR in STEMI patients without diabetes (nondiabetic subgroup)." (PMID 37061678, 2023). "A meta-analysis of clinical trials upon individuals with and without diabetes, compared the effect of prolonged sitting time with moments of physical activity throughout the day (INT) to continuous sitting (SIT) on serum glucose, insulin, and triglyceride (TG) levels." (PMID 36593495, 2023).
diabetes (continued). "Thus, we base our conclusion that MEB did not affect insulin sensitivity compared with COMP on the more comprehensive metric of Matsuda index, but also recognize that glucose tolerance based on glucose AUC is widely used to diagnosis diabetes." (PMID 37513677, 2023). "A systematic review of intensive insulin therapy showed that high blood sugar was not predictive of SSI among diabetic patients and recommended a target blood glucose level of <150 mg/dl (<8.3 mmol/l) in patients without diabetes undergoing gastroenterological surgery." (PMID 36310325, 2023). "However, diabetes in SSA may have a different etiology, as suggested by data showing a high prevalence of diabetes in non-overweight people and low insulin secretion as well as insulin resistance." (PMID 37266136, 2023). "Previous literature suggests that because the kidney is responsible for the majority of exogenous insulin clearance, patients with diabetes and CKD and lower renal clearance rates have higher levels of serum insulin and may require less insulin than those without CKD." (PMID 35189851, 2022). "In a mouse model of slowly progressive diabetes that does not show hyperglycemia until four weeks following low doses STZ administration, SDC4-KO mice showed hyperglycemia from four days after STZ administration and reduced casual insulin secretion and pancreatic β-cell mass." (PMID 36292936, 2022). "This could be attributed to the fact that probably diabetes management in type 1 diabetes largely depends on performing regular blood glucose monitoring using glucometers or CGM systems and adequate administration of insulin therapy, unlike type 2 diabetes." (PMID 36141404, 2022). "Finally, insulin does not appear to protect against early changes in OGF levels or estrogen secretion in diabetic female rats, setting the stage for a distinction in the disease profile of diabetes between males and females." (PMID 36274979, 2022). "Although insulin is not required by all patients with T2DM, it might be indispensable to achieve good glycemic control, due to a progressive decline in beta-cell function or to the failure of oral anti-diabetes drugs (OADs)." (PMID 36483894, 2022). "Glycaemia, insulin, and the HOMA-IR index were similarly increased in elderly and LD patients relative to controls, indicating that although there was no overt diabetes in these groups, they showed similar alterations in glucose/insulin homoeostasis that are reminiscent of insulin resistance." (PMID 35300561, 2022). "4.Prescribe corticosteroids to pregnant patients with diabetes mellitus (whether they have CKD or not) to promote fetal lung maturation only in clinical setting due to the need for intensive blood sugar monitoring and frequent insulin adjustments." (PMID 36506226, 2022). "However, as Smad2 also plays an essential role in the glucose-stimulated release of insulin in β cells 16, targeting Smad3 but not upstream TGFBR1 in islets (β cells) may be more favorable for cell replacement treatment of diabetes." (PMID 34987651, 2022). "Our study also presents some limitations since the animal model of diabetes induced by STZ used has some physiopathological differences with human GDM that may include insulin treatment requirement, absence of increased insulin resistance, or foetal growth restriction among others." (PMID 34156347, 2021). "The reduction of AMA in prevalent diabetes and a negative correlation of AMA to the glucose level are in a good agreement with present literature data suggesting impaired Chromogranin A amidation in diabetes, thus reducing insulin granule packaging and secretion." (PMID 34349173, 2021). "In a case-control study, the first-degree offspring of patients with type 2 diabetes had reduced total insulin sensitivity and impaired beta-cell function, both of which were related to increased internal carotid artery IMT, compared to individuals without a family history of diabetes." (PMID 34525777, 2021).
diabetes (continued). "Protection from diabetes in NOD mice lacking Ins1 is likely due to the absence of cognate antigen in the target tissue, indicating that PIns1 peptides may be primarily targeted by insulin reactive T cells." (PMID 33841427, 2021). "Since we found that increased CLU levels in pancreas and liver from the tissue specific CLU Tg mice do not induce premature onset of diabetes but exacerbate INS intolerance, we suggest that pancreas specific CLU upregulation may result in deregulation of the GLU-INS metabolic pathway." (PMID 33744871, 2021). "A complete amelioration of diabetes induced by adrenal insufficiency was reported in patients with type 2 diabetes, but it has never been reported in a patient with T1DM with decreased insulin secretory capacity to an insulin-dependent level as observed in our patient." (PMID 33892782, 2021). "Data from the literature have shown that CFRD and type 2 diabetes mellitus (T2DM) have overlapping etiology and pathophysiological mechanisms, mainly represented by impaired pancreatic β cells with decreased insulin secretion, rather than decreased insulin sensitivity." (PMID 34945117, 2021). "Instead, in subjects with T2DM the insulin secretion did not increase when compared with GLP-1 infusion alone, but there was an increase when compared with GIP and placebo administration, emphasizing the reduced insulinotropic effect of GIP in patients with diabetes." (PMID 35054422, 2021). "AGEs can be “trapped” in adipose tissue, even in the absence of diabetes, in part due to higher expression of the receptor for AGEs (RAGE) and/or decreased detoxification by the endogenous glyoxalase (GLO) system, where they may promote insulin resistance." (PMID 34103691, 2021). "Although several previous studies have suggested that the initial insulin dose in an ITT could be determined based on BMI, pre-test BG, with or without diabetes, acromegaly or suspected Cushing's syndrome, there have been no personalized calculation methods for insulin dosage until now." (PMID 32328036, 2020). "We assessed fasting serum OPG, high-sensitive C-reactive protein (hsCRP), glucose, insulin and lipid profile in patients having T2DM receiving oral antidiabetic drugs (OAD) (n = 42) compared with age, gender and body composition-matched healthy participants without diabetes (n = 42)." (PMID 33081726, 2020). "In the United Kingdom Prospective Diabetes Survey involving 3,672 patients with T2D, GADA (defined as titer >20 U/L by a radioimmunoprecipitation assay) was present in 9.8% of adult patients, who were more likely to require insulin within 6 years of diagnosis than those without GADA." (PMID 32722720, 2020). "Furthermore, staff nurses may not have a sense of responsibility of using the insulin PDA as they are on rotation and may perceived that it is the diabetes educators’ responsibility." (PMID 33378349, 2020). "Among the 129 patients with diabetes mellitus type 2 (according to the ADA definition), 54 received oral medical treatment, 10 received insulin treatment alone, 30 received a combination of oral treatment and insulin, and 35 did not receive any medication for their diabetes." (PMID 32314253, 2020). "In a study of pre-diabetic obese women with increased risk for EC, MET intake for 16 weeks produced no significant changes in serum IGF-I and insulin, suggesting that the changes in serum levels of these growth factors with MET may be a specific response of EC patients with full-blown diabetes." (PMID 32046384, 2020). "In type 1 diabetes mellitus (T1DM), hyperglycemia – the most prominent feature of this pathology – is a result of both the impaired glucose uptake by insulin-dependent tissues and the hyperactive production of glucose by the liver, due to the lack of insulin release by pancreatic beta cells." (PMID 31859908, 2020).
diabetes (continued). "The transplanted, intrahepatic islets showed strongly positive staining for insulin; the absence of insulin-positive islet beta cells in the native pancreas at necropsy indicated that posttransplant normoglycemia reflected graft function and was not due to remission after STZ-induced diabetes." (PMID 31375697, 2019). "High glucose AGE-modified ECM significantly decreased insulin-stimulated glucose uptake relative to low glucose-conditioned ECM in both NDM and DM ECM-adipocyte cultures but did not affect basal glucose uptake, even after controlling for diabetes status, age and sex." (PMID 31875018, 2019). "Four NASH and 1 SS patients who were taking anti-diabetic drugs (none were on insulin therapy) as well as 3 patients with HOMA-IR >15 (possibly a consequence of non-fasting before the blood test), were excluded from analyses related to diabetes parameters (HbA1c, HOMA-IR)." (PMID 29362454, 2018). "We are currently conducting a larger study with age and BMI matched Non-DM participants and T2DM participants that do not take diabetes medications that use an insulin infusion protocol of 600 pmol/L and involves an analysis of the genome of SLC30A8." (PMID 29791512, 2018). "Moreover, obesity itself might not be a decisive factor of diabetes in PWS, considering the low visceral fat distribution and relative low insulin resistance compared to obese individuals without PWS." (PMID 28854950, 2017). "Likewise, the absence of fasting insulin, HOMA-IR, and HOMA-Beta may reduce the possibility of screening all patients with diabetes." (PMID 29020963, 2017). "The clinical relevance of GA could be attributed to observations that increased GA rather than HbA1C is significantly correlated with insulin secretory beta-cell function as assessed by PCGR and HOMA-β and that GA increases as the duration of diabetes lengthens." (PMID 28122570, 2017). "CSE could not significantly improve any of the late stage diabetes conditions; however, if CSE’s mechanism of anti-inflammatory and anti-hyperglycemic activities is mediated by insulin, it may benefit patients with LT2D who inject insulin." (PMID 26877773, 2016). "In addition, in participants without diabetes, LLS offspring had a favourable glucose-insulin homeostasis, and in the total study population, LLS offspring had a beneficial lipid profile, lower thyroid function, altered mTOR signalling, and a lower serum level of 25-hydroxyvitamin D." (PMID 27540764, 2016). "A recent study demonstrated that nicotine infusion acutely impairs insulin sensitivity in people with T2DM, but not in healthy subjects suggesting that smoking might affect people with diabetes differently compared to people who do not have diabetes." (PMID 27881170, 2016). "Diabetes mellitus (DM) refers to a condition of hyperglycemia that can be further classified into T1DM, primarily due to a lack of insulin, or T2DM, primarily due to peripheral insulin resistance." (PMID 25759846, 2015). "This study investigated whether pancreatic insulin-producing cells (IPCs) differentiated from hESCs could correct hyperglycemia in severe combined immunodeficient (SCID)/non-obese diabetic (NOD) mice, an animal model of diabetes." (PMID 25009980, 2014). "We aimed to test whether UCPCR could be used as a surrogate measure of insulin resistance in epidemiological studies by examining the correlation of UCPCR with fasting serum insulin, C-peptide and HOMA2-IR (HOMA2-insulin resistance) in participants without diabetes." (PMID 24353253, 2013). "Based on our criteria for diabetes (fasting glucose ≥ 250 mg/dl), the successful rate of 25 mg/kg BW STZ group was significantly high and the rats presented a typical characteristic of T2DM as hyperglycemia, IR, and blood lipid disorder, but without decreased serum insulin level (data not shown)." (PMID 23870481, 2013).